APOBEC1 (apolipoprotein B mRNA editing enzyme catalytic subunit 1)
Description:
Cytidine deaminase catalyzing the cytidine to uridine postranscriptional editing of a variety of mRNAs. Form complexes with cofactors that confer differential editing activity and selectivity. Responsible for the postranscriptional editing of a CAA codon for Gln to a UAA codon for stop in the apolipoprotein B mRNA. Also involved in CGA (Arg) to UGA (Stop) editing in the NF1 mRNA. May also play a role in the epigenetic regulation of gene expression by participating in DNA demethylation (By similarity).
Synonyms: APO1; APOBEC-1; BEDP; CDAR1; HEPR
Tractability: No criterion of Open Targets' tractability assessment is met for any kind of drug.
Gene: Protein-coding gene on chromosome 12 (7,649,400 to 7,665,908, reverse strand). Ensembl gene ENSG00000111701.
Subcellular location: Cytoplasm; Nucleus
Pathways (Reactome):
Metabolism of RNA: Formation of the Editosome; mRNA Editing: C to U Conversion
Gene Ontology:
Molecular function: protein binding; cytidine deaminase activity; RNA binding; zinc ion binding; hydrolase activity; mRNA 3'-UTR AU-rich region binding
Biological process: cytidine to uridine editing; mRNA modification; negative regulation of nuclear-transcribed mRNA catabolic process, nonsense-mediated decay; chromosomal 5-methylcytosine DNA demethylation pathway; lipid metabolic process; positive regulation of gene expression via chromosomal CpG island demethylation; regulation of mRNA metabolic process
Cellular component: apolipoprotein B mRNA editing enzyme complex; cytoplasm; nucleus; mRNA editing complex; nucleoplasm
Genetic constraint (gnomAD): Loss-of-function variants: 18 observed, 24.57 expected, observed/expected ratio (o/e) 0.73, 90% interval 0.5 to 1.09. The upper end of that interval is the gene's LOEUF score, 1.09, which puts it in group 4 of 6, group 1 being the genes least tolerant of losing a copy. Missense variants: 234 observed, 278.99 expected, observed/expected ratio (o/e) 0.84, 90% interval 0.75 to 0.94. Synonymous variants: 69 observed, 92.01 expected, observed/expected ratio (o/e) 0.75, 90% interval 0.62 to 0.92.
Homologues: Orthologues: chimpanzee APOBEC1 (98% identical), macaque APOBEC1 (94% identical), pig APOBEC1 (79% identical), rabbit APOBEC1 (76% identical), mouse Apobec1 (69% identical), guinea pig APOBEC1 (68% identical), rat Apobec1 (64% identical). Paralogues in human: APOBEC3G (25% identical), APOBEC3F (24% identical), APOBEC3D (24% identical), APOBEC3B (22% identical), AICDA (22% identical), APOBEC3A (20% identical), APOBEC3C (20% identical), APOBEC2 (19% identical), APOBEC3H (18% identical).
Diseases named in the same sentence as APOBEC1 in open-access papers:
APOBEC1 is named in the same sentence as 55 diseases in open-access papers, as found by Europe PMC text mining. Sharing a sentence is not in itself a finding about the gene and the disease. The quoted sentences say what the papers report.
hepatocellular carcinoma (11 papers, 2007 to 2025). A malignant tumor that arises from hepatocytes. "Overexpression of Apobec1 in mice and rabbits leads to hepatocellular carcinomas showing hyper-editing of multiple cytosines at different sites other than the canonical one on the ApoB mRNA, suggesting that high levels of APOBEC1 result in the loss of editing fidelity." (PMID 38001542, 2023). "APOBEC1 expression has been linked to cancer: transgenic mice and rabbits constitutively expressing APOBEC1 in the liver develop hepatocellular carcinoma, and APOBEC1 deficiency in cancer-prone APCmin mice reduces the number of polyps and tumors in the gastrointestinal tract." (PMID 25085003, 2014). "APOBEC1 overexpressing mice develop liver carcinomas, but these animals were reported to contain 3 to 17 transgenes." (PMID 40213992, 2025). "Recently, Sparcl1 was reported to be upregulated in liver-specific Apobec1 complementation factor transgenic mice, which is charactered with a phenotype with spontaneous steatosis, fibrosis, and hepatocellular cancer." (PMID 36387870, 2022). "For transgenic mice expressing the rabbit APOBEC1 gene under the control of a liver specific promoter, hepatic dysplasia and hepatocellular carcinomas were found." (PMID 19843348, 2009). "For example, the over-expression of APOBEC-1 in mouse livers led to liver dysplasia and hepatocellular carcinomas, a phenomenon that has been attributed to promiscuous editing of mRNAs other than APOB." (PMID 17233885, 2007). "However, APOBEC1 editing fidelity was found to be severely compromised when the protein was overexpressed in rat hepatomas." (PMID 18577210, 2008). "Similarly, overexpression of APOBEC1 in transgenic rabbits and mice led to extensive non-specific editing of apoB mRNA as well as other mRNAs and was associated with liver dysplasia and hepatocellular carcinomas." (PMID 18577210, 2008). "An early study found that transgenic mice and rabbits expressing rabbit APOBEC1 in their livers developed hepatocellular carcinomas, while controls did not." (PMID 38254863, 2024).
atherosclerosis (8 papers, 2014 to 2025). A disease characterized by the build-up of fatty material and calcium deposition in the arterial wall resulting in partial or complete occlusion of the arterial lumen. "A recent genome-wide association study (GWAS) identified novel SNPs at APOBEC1 that are associated with cholesterol composition, signifying APOBEC1's role in cholesterol-linked human diseases, such as atherosclerosis." (PMID 30619092, 2018). "One candidate gene within the Chromosome 6 peak region associated with atherosclerosis is Apobec1, the apolipoprotein B (ApoB) mRNA-editing enzyme, which plays a role in the regulation of ApoB, a critical component of low-density lipoprotein, by editing ApoB mRNA." (PMID 25344410, 2014). "This locus contains the candidate gene Apobec1 which is known to alter circulating lipoprotein composition, but also has widespread RNA editing capabilities, perhaps indicating an additional mechanism by which susceptibility to atherosclerosis is regulated." (PMID 25344410, 2014). "We next hypothesized that the association at this locus may be mechanistically related to the role of Apobec1 in editing its primary target, ApoB, as elevated plasma ApoB is a known risk factor for atherosclerosis." (PMID 25344410, 2014). "An elevated level of apoB100-containing LDL in the plasma is one of the major characteristics in patients with atherosclerosis, a disease state mimicked by mouse models that either lose APOBEC1's RNA editing activity or express apoB100 exclusively." (PMID 30619092, 2018). "High-fat induced upregulation of APOBEC1 and its roles in rabbit atherosclerosis is worth further study." (PMID 30067832, 2018). "Using a DO mouse population fed an HFCA diet, we were able to identify an A/J-specific isoform of Apobec1 that contributes to atherosclerosis." (PMID 25344410, 2014). "Apobec1 is an attractive candidate gene for influencing diet-induced lesion size based on the known function of Apobec1 in lipid homeostasis and a causal allele for Apobec1 has not been previously identified as associated with atherosclerosis." (PMID 25344410, 2014).
breast carcinoma (3 papers, 2013 to 2022). "In addition, except the APOBEC3H gene, we found high DNA methylation levels of the remaining APOBEC members, including APOBEC1, APOBEC2, APOBEC3A, APOBEC4, and AICDA, in both HMEC and ER− breast cancer cells." (PMID 26682542, 2015). "However, none of the deaminases analysed to date (AID, APOBEC1, APOBEC3C, 3DE, 3F and 3G) has been shown to exhibit a preference that accords with the breast cancer kataegic mutations." (PMID 23599896, 2013). "For other APOBEC family members, they show either extremely low (median log2-transformed RPKM < 0) mRNA levels (including APOBEC3A, APOBEC3H, APOBEC1, APOBEC2, APOBEC4, and AICDA), or no obvious expression differences between ER+ and ER− breast cancers (including APOBEC3D, APOBEC3F, and APOBEC3G)." (PMID 26682542, 2015).
epilepsy (3 papers, 2017 to 2025). A brain disorder characterized by episodes of abnormally increased neuronal discharge resulting in transient episodes of sensory or motor neurological dysfunction, or psychic dysfunction. "APOBEC1 dimorphism as a new genetic risk factor of epilepsy." (PMID 41446042, 2025).
esophageal adenocarcinoma (3 papers, 2014 to 2025). A malignant tumor with glandular differentiation arising predominantly from Barrett mucosa in the lower third of the esophagus. "Moreover, we find the presence of an AID/APOBEC mutational signature in esophageal adenocarcinomas, a type of tumor where APOBEC1 is expressed, that mimics the one preferred by APOBEC1 in vitro." (PMID 25085003, 2014). "In addition, we show the presence of the mutational signature of the AID/APOBECs in human esophageal adenocarcinomas, a type of tumor in which APOBEC1 is highly expressed." (PMID 25085003, 2014). "Such APOBEC1-induced mutator phenotypes could play a role in the onset of esophageal adenocarcinomas." (PMID 25085003, 2014). "APOBEC1 could be involved in cancer promotion at the very early stages of carcinogenesis, as it is highly expressed in Barrett's esophagus, a condition often associated with esophageal adenocarcinoma." (PMID 25085003, 2014). "A strong association between human APOBEC1 expression and the APOBEC mutational signature was found in esophageal adenocarcinomas and APOBEC1 expression was also correlated with indel mutations in many tumor genomes." (PMID 31726973, 2019).
Obesity (3 papers, 2014 to 2023). Accumulation of substantial excess body fat. "Most of these studies have targeted the extensively studied APOBEC-mediated C-to-U editing event that occurs in mammalian APOBEC1 mRNA, revealing the influence of ethanol intake, insulin, obesity, and diet on APOBEC1 mRNA editing levels." (PMID 26637431, 2015). "With the aim to show that APOB mRNA editing is a target mechanism for fighting against obesity, we searched to modulate APOBEC1 enzymatic activity in vivo in the rabbit species by modulating APOBEC1 gene expression through transgenesis." (PMID 25216115, 2014). "This suggests that the APOBEC1 gene might be a novel target for obesity treatment." (PMID 25216115, 2014). "In the search of new targets for obesity, we have investigated the APOB mRNA editing protein (APOBEC1) gene pathway that is involved in fat absorption in the intestine." (PMID 25216115, 2014).
viral infections (3 papers, 2020 to 2021). "OASL, a member of the OAS protein family, like APOBEC1, is associated to the innate immune defense against viral infections." (PMID 32545414, 2020). "Although our mutational spectrum is quite similar to the pattern of mutations caused by APOBEC1 ([A/U]p[C→U]p[A/U]), the enzyme is exclusively expressed in the small and large intestine, which is not a predominant target organ for this viral infection." (PMID 34453107, 2021).
carcinomas of the stomach (2 papers, 2006 to 2024). "In human carcinomas of the stomach, pancreas, large intestine and liver alterations in the expression of an RNA-specific cytidine deaminase, APOBEC-1, that is involved in RNA editing were also reported." (PMID 16404425, 2006).
colorectal cancer (2 papers, 2022). A primary or metastatic malignant neoplasm that affects the colon or rectum. "As a higher transcript level of a catalytically inactive, shorter APOBEC1 splice-variant has been observed in colorectal cancer before, the elevated mRNA expression level also detected in our study may not have an effect on the global DNA methylation level." (PMID 35655145, 2022).
dysplasia (2 papers, 2009 to 2018). A usually neoplastic transformation of the cell, associated with altered architectural tissue patterns. "Historically, transgenic mice and rabbits expressing mRNA editing enzyme APOBEC-1 (C-to-U editing) resulted in unexpected liver dysplasia, with a few of the mice developing HCC." (PMID 30521023, 2018).
familial hypercholesterolemia (2 papers, 2019 to 2021). An inheritable form of hyperlipidemia, in which there are excess lipids in the blood. "Considering how central APOB editing is for cholesterol transport in the blood—Apobec1 deficient mice display hypercholesterolemia—mutations/polymorphisms in Apobec1 might increase the risk of cardiovascular diseases." (PMID 33376192, 2021).
liver cancer (2 papers, 2020 to 2022). An epithelial or non-epithelial malignant neoplasm that arises from the liver. "APOBEC1 was first connected to cancer when transgenic mice and rabbits expressing the protein in their livers developed liver cancer." (PMID 32545414, 2020).
testicular germ cell tumor (2 papers, 2018). A germ cell tumor arising from the testis. "Although more investigations are needed to confirm the roles of these APOBEC1 partners in APOBEC1-regulated cancer development, an interesting study using a mouse model of testicular germ cell tumors (TGCTs) hinted strongly at such connections." (PMID 30619092, 2018). "Dnd1ter mutant mice develop testicular germ cell tumors (TGCT), whose incidence can be modulated by the dosage of an Apobec1-null allele." (PMID 30591678, 2018).
thyroid carcinoma (2 papers, 2022). "It has been reported that high expression of APOBEC1 is associated with poor prognosis of adrenocortical carcinoma, endometrial carcinoma, mesothelioma and thyroid carcinoma." (PMID 36339709, 2022). "The expression levels of APOBEC1 can be used to predict pancancer outcomes, particularly for patients with pancreatic and thyroid carcinoma." (PMID 36081904, 2022).
cervical carcinoma (1 paper, 2020). A carcinoma arising from either the exocervical squamous epithelium or the endocervical glandular epithelium. "Therefore, we also integrated the APOBEC family (APOBEC1 APOBEC3A, APOBEC3B, APOBEC3C, APOBEC3D, APOBEC3F, APOBEC3G, and APOBEC3H) mRNA expression of 176 core-set cervical carcinoma samples for multiplatform integrative analyses." (PMID 32211324, 2020).
colon cancer (1 paper, 2021). "The association of APOBEC1 in human gastrointestinal tumors and colon cancer-derived cell lines was initially reported some 20 years ago." (PMID 34316699, 2021).
esophageal cancer (1 paper, 2022). A primary or metastatic malignant neoplasm involving the esophagus. "Changes related to APOBEC1 mutation activity may enhance its carcinogenic potential and promote the occurrence and development of many cancers, including gastrointestinal tumors and esophageal cancer." (PMID 36339709, 2022).
Menkes disease (1 paper, 2025). A usually severe multisystemic disorder of copper metabolism, characterized by progressive neurodegeneration and marked connective tissue anomalies as well as typical sparse abnormal steely hair. "Here, we generated plasmids encoding the MS2 system and the APOBEC1 deaminase domain and used a guide RNA with flanking MS2 sites to restore mutated Atp7a in fibroblasts from a macular mouse model of Menkes disease withs T>C mutation." (PMID 39858530, 2025).
myocardial ischemia (1 paper, 2024). A disorder of cardiac function caused by insufficient blood flow to the muscle tissue of the heart.
ovarian carcinoma (1 paper, 2016). A malignant neoplasm originating from the surface ovarian epithelium. "APOBEC1, APOBEC2 and DPPA3 mRNAs were not expressed or expressed at the detection limit in the ovarian cancer tissues of the herein investigated cohort of patients and therefore those variables were excluded from the univariate Cox regression and all subsequent analyses." (PMID 27527602, 2016).
pancreatic adenocarcinoma (1 paper, 2022). "APOBEC1/3A/3G/3H had genetic variation in 5 samples (3%) from patients with pancreatic adenocarcinoma, of which the gene with the highest frequency of mutation is APOBEC1 (2%), and the main type of variation is amplification." (PMID 36339709, 2022). "To further explore the mechanisms of APOBEC1/3A/3G/3H in the occurrence and development of PAAD, we first obtained 400 coexpressed genes of APOBEC1/3A/3G/3H in pancreatic adenocarcinoma from the LinkedOmics database and generated the volcano map." (PMID 36339709, 2022). "The results showed that there was a significant correlation between the amplification variation of APOBEC1/3A/3G/3H and the invasion of surrounding tissues of pancreatic adenocarcinoma." (PMID 36339709, 2022). "To further explore the mechanism of the differential expression of APOBEC1/3A/3G/3H in pancreatic adenocarcinoma, we used the cBioPortal online tool to analyze the gene variation of APOBEC1/3A/3G/3H." (PMID 36339709, 2022). "First, we analyzed the difference in APOBEC1/3A/3G/3H expression between pancreatic adenocarcinoma samples, matched adjacent samples and normal pancreatic tissues using The Cancer Genome Atlas (TCGA) and Genotype-Tissue Expression (GTEx) databases." (PMID 36339709, 2022). "However, the function of APOBEC1/3A/3G/3H in pancreatic adenocarcinoma (PAAD) is still unclear." (PMID 36339709, 2022). "However, the role of APOBEC1, APOBEC3A, APOBEC3G and APOBEC3H in pancreatic adenocarcinoma is not clear, and related studies are very scarce, which motivated us to carry out relevant bioinformatics analysis." (PMID 36339709, 2022).